AMPD1 (adenosine monophosphate deaminase 1)
Description:
AMP deaminase plays a critical role in energy metabolism.
Synonyms: MAD; MADA; MMDD
Tractability: Small molecule: it belongs to a druggable protein family. PROTAC: ubiquitination databases record sites on it; a small molecule that binds it is known.
Target class: Enzyme; Hydrolase
Safety:
Unwanted effects reported when the protein is acted on. In parentheses: how it was acted on, where the effect was seen, and who reports it.
CNS adverse events (source: ClinPGx)
elevation in systolic blood pressure (source: ClinPGx)
elevation in systolic blood pressure and a incidence of side effects (source: ClinPGx)
incidence of side effects (source: ClinPGx)
response to methotrexate (source: ClinPGx)
Gene: Protein-coding gene on chromosome 1 (114,673,090 to 114,695,618, reverse strand). Ensembl gene ENSG00000116748.
Pathways (Reactome):
Metabolism: Purine salvage
Gene Ontology:
Molecular function: AMP deaminase activity; identical protein binding; protein binding; deaminase activity
Biological process: GMP salvage; AMP metabolic process; IMP biosynthetic process; IMP salvage; nucleoside phosphate metabolic process; purine ribonucleoside monophosphate biosynthetic process
Cellular component: cytosol
Genetic constraint (gnomAD): Loss-of-function variants: 71 observed, 83.53 expected, observed/expected ratio (o/e) 0.85, 90% interval 0.7 to 1.04. The upper end of that interval is the gene's LOEUF score, 1.04, which puts it in group 4 of 6, group 1 being the genes least tolerant of losing a copy. Missense variants: 875 observed, 968.62 expected, observed/expected ratio (o/e) 0.9, 90% interval 0.85 to 0.95. Synonymous variants: 333 observed, 339.9 expected, observed/expected ratio (o/e) 0.98, 90% interval 0.89 to 1.07.
Homologues: Orthologues: chimpanzee AMPD1 (99% identical), macaque AMPD1 (97% identical), rabbit AMPD1 (94% identical), pig AMPD1 (93% identical), mouse Ampd1 (93% identical), rat Ampd1 (93% identical), dog AMPD1 (92% identical), guinea pig AMPD1 (92% identical), tropical clawed frog ampd1 (72% identical), zebrafish ampd1 (70% identical). Paralogues in human: AMPD3 (61% identical), AMPD2 (50% identical).
Diseases named in the same sentence as AMPD1 in open-access papers:
AMPD1 is named in the same sentence as 54 diseases in open-access papers, as found by Europe PMC text mining. Sharing a sentence is not in itself a finding about the gene and the disease. The quoted sentences say what the papers report.
breast carcinoma (8 papers, 2020 to 2023). "For example, adenosine monophosphate deaminase 1 (AMPD1) and ribonucleotide reductase regulatory subunit M2 (RRM2), which are involved in purine metabolism, have been associated with survival in breast cancer patients." (PMID 38169859, 2023). "In breast cancer, a study showed that AMPD1 expression was closely linked to tumor-infiltrating immune cells and prognosis outcomes in HER2-positive breast cancer and that it may serve as a potential biomarker." (PMID 36439484, 2022). "AMPD1 could be regarded as the biomarker to predict the survival of breast cancer." (PMID 32953885, 2020). "Purine metabolism and related genes AMPD1 and RRM2 were enriched by combining metabolomics and transcriptomics data from the TCGA and GEO in breast cancer." (PMID 34549263, 2021).
diabetes (4 papers, 2014 to 2025). "Interestingly, AMPD1 was also reported as a putative target of the diabetes drug metformin, and AMPD1 deficient individuals have been reported to have decreased rates of diabetes." (PMID 30837873, 2019). "It is also worth noting that our study from 2009 revealed that the AMPD1:rs17602729 polymorphism was associated with a decreased frequency of obesity in Polish patients with coronary artery disease (CAD) and with decreased diabetes prevalence in CAD patients with heart failure." (PMID 40869391, 2025). "Among these, Paraoxonase-1 (PON1), AMP deaminase-1 (AMPD1) and Annexin 1 (ANXA1) are involved in diabetes or GDM." (PMID 34416903, 2021).
endometritis (4 papers, 2023 to 2025). An acute or chronic, usually bacterial infectious process affecting the endometrium. "The expression levels of the genes TLR4, TLR7, TNF-α, NCF4, LITAF, OXSR1, TKT, RPIA, and AMPD1 were significantly greater in endometritis-affected Holstein dairy cows than in resistant ones." (PMID 37368756, 2023). "Molecular genetic analyses of the immunological (TLR4, TLR7, TNF-α, IL10, NCF4, and LITAF), antioxidant (ATOX1, GST, and OXSR1), and erythritol-related (TKT, RPIA, and AMPD1) genes comparing healthy and endometritis cows found differences in nucleotide sequence and transcript levels." (PMID 37368756, 2023). "The immune (TLR4, TLR7, TNF-α, IL10, NCF4, and LITAF), antioxidant (ATOX1, GST, and OXSR1), and erythritol-related (TKT, RPIA, and AMPD1) genes in endometritis-affected and healthy Holstein dairy cows were characterized in this research using a PCR-DNA sequencing technique." (PMID 37368756, 2023). "Single nucleotide variants (SNPs) in the genes were discovered using PCR-DNA sequencing for immune (TLR4, TLR7, TNF-α, IL10, NCF4, and LITAF), antioxidant (ATOX1, GST, and OXSR1), and erythritol-related (TKT, RPIA, and AMPD1) genes found in resistant and endometritis-infected Holstein dairy cows." (PMID 37368756, 2023). "Compared to resistant cows, endometritis-affected cows produced considerably more of the genes TLR4, LITAF, TNF-α, TKT, RPIA, TLR7, TNF-α, TKT, and AMPD1." (PMID 39195794, 2024). "Gene expression levels were considerably higher in endometritis-affected cows than in resistant ones for the genes TLR4, TLR7, TNF-α, NCF4, LITAF, OXSR1, TKT, RPIA, and AMPD1." (PMID 37368756, 2023). "Nucleotide sequence variations between healthy and endometritis-affected cows were revealed using PCR-DNA sequencing for immune (TLR4, TLR7, TNF-α, IL10, NCF4, and LITAF), antioxidant (ATOX1, GST, and OXSR1), and erythritol-related (TKT, RPIA, and AMPD1) genes were reported by44." (PMID 38459095, 2024). "Nucleotide sequence variations between healthy and endometritis-affected cows were revealed using PCR-DNA sequencing for immune (TLR4, TLR7, TNF-α, IL10, NCF4, and LITAF), antioxidant (ATOX1, GST, and OXSR1), and erythritol-related (TKT, RPIA, and AMPD1) genes." (PMID 37368756, 2023).
heart failure (4 papers, 2014 to 2019). Inability of the heart to pump blood at an adequate rate to meet tissue metabolic requirements. "Current evidence indicates that the common AMPD1 gene variant is associated with improved survival in patients with advanced heart failure." (PMID 29095874, 2017). "In heart failure patients, genetic AMPD1 deficient subjects exhibited decreased systolic blood pressure, an increase in cardiac output (left ventricular ejection fraction), and improved heart failure prognosis." (PMID 30837873, 2019). "Several studies identified that polymorphism of AMP deaminase 1 gene (AMPD1), in particular the common C34T variant of this gene was found to benefit patients with heart failure and ischemic heart disease." (PMID 24431031, 2014).
metabolic myopathy (4 papers, 2010 to 2023). A group of rare inherited disorders characterized by a deficiency of enzymes that are involved in metabolic pathways that affect muscles. "This enzyme activity is presumed to be important in skeletal muscle because a metabolic myopathy develops in individuals with an inherited deficiency of AMPD1." (PMID 34828287, 2021). "Finally, seven proteins were associated with metabolic myopathy where Cacna1s, Ampd1, Pygm, Gys1, and Pfkm were upregulated and where Gbe1 and Ca2 were downregulated." (PMID 34828261, 2021). "This includes PYGM-deficiency (McArdle disease); lack of AMPD1, which causes metabolic myopathy in humans; and loss-of-function mutations in the CAPN3 gene that have been associated with limb-girdle muscular dystrophy type 2A (LGMD2A)." (PMID 20175888, 2010). "A lack of AMPD1, the muscle-specific isoform of AMPD (myoadenylate deaminase deficiency), can cause a metabolic myopathy, with exercise-induced muscle symptoms such as early fatigue, cramps, and/or myalgia." (PMID 37512494, 2023).
Coronary Artery Disease (3 papers, 2013 to 2025). "Some reports indicated the association of rs17602729 and rs34526199 functional polymorphisms of the AMPD1 gene encoding adenosine monophosphate deaminase 1 (AMPD1) with the risk of coronary artery disease (CAD) and/or its intermediate phenotype." (PMID 40869391, 2025).
Insulin resistance (3 papers, 2014 to 2019). Increased resistance towards insulin, that is, diminished effectiveness of insulin in reducing blood glucose levels. "We reported that the diet-induced insulin resistance was improved in AMPD1-deficient mice compared to wild type mice." (PMID 25887856, 2015). "We demonstrated that AMPD1 deficient mice show augmented glucose tolerance and attenuated insulin resistance under high fat diet feeding triggering insulin resistance." (PMID 25887856, 2015). "Since these results suggest that AMPD1 deficiency inhibits the attenuation of insulin signaling in skeletal muscle under high fat diet feeding, they support the notion that AMPD1 deficiency attenuates insulin resistance induced by high fat diet feeding." (PMID 25887856, 2015). "We showed in the previous report that the deficiency of AMPD1 which is highly selectively expressed in skeletal muscle attenuates insulin resistance induced by high fat diet feeding in C57BL6 mice that is an experimental model for insulin resistance." (PMID 25887856, 2015). "Therefore, we studied AMPK/Akt/mTORC1/p70 S6 kinase axis in skeletal muscle after high fat diet challenge in AMPD1-deficient mice to show the impact of AMPD1 on insulin resistance." (PMID 25887856, 2015). "We demonstrated that AMPD1 deficiency enhances activation of AMPK/Akt/mTORC1/p70 S6 kinase pathway in skeletal muscle under high fat diet feeding that could potentially contribute to attenuated insulin resistance, in accordance with our previous report using an in vivo experimental model." (PMID 25887856, 2015). "Disruption of the AMPD1 gene leads to a less severe state of insulin resistance, improved glucose tolerance and enhanced insulin clearance in mice fed a high fat diet." (PMID 25511531, 2014). "Skeletal muscle is one of the primary organs contributing to insulin resistance and that the AMPD1 gene is selectively expressed at high levels in skeletal muscle." (PMID 25511531, 2014). "Because of the central role skeletal muscle plays in insulin resistance and because AMPD1 is predominately expressed in this tissue, fat content of the skeletal muscle was assessed." (PMID 25511531, 2014). "Recognizing the background above, we asked if genetic disruption of the AMPD1 gene might ameliorate the manifestations of insulin resistance." (PMID 25511531, 2014).
Obesity (3 papers, 2020 to 2025). Accumulation of substantial excess body fat. "The results of the present work have confirmed our previous findings regarding the association of the c.34C>T AMPD1 polymorphism with BMI and obesity." (PMID 40869391, 2025). "BMI and the frequency of obesity in TT rs17602729 homozygotes (no AMPD1 activity) were significantly lower and the serum concentration of HDL cholesterol was significantly higher compared to other patients." (PMID 40869391, 2025). "The BMI and the frequency of obesity in patients with no AMPD1 activity were significantly lower compared to other patients (e.g., patients with full or intermediate activity of AMP deaminase 1)." (PMID 40869391, 2025). "On the other hand, some studies did not confirm relationship between AMPD1 genotype and obesity-related traits." (PMID 32429460, 2020). "In the study, differences in obesity-related traits across the AMPD1 genotypes and genotype × training interactions were also not found." (PMID 32429460, 2020).
adenosine monophosphate deaminase deficiency (2 papers, 2008 to 2023). Adenosine monophosphate (AMP) deaminase deficiency is a metabolic disorder for which two forms have been described. "Although 1–2% of the Caucasian population carries one of the mutations that cause myoadenylate deaminase deficiency, few carriers show symptoms and the clinical relevance of AMPD1 deficiency has been questioned." (PMID 37512494, 2023).
autism (2 papers, 2016). Persistent deficits in social interaction and communication and interaction as well as a markedly restricted repertoire of activity and interest as well as repetitive patterns of behavior. "In the SFARI autism database, the following DE genes were registered: Celf6, which codes for a transcription associated protein and was common to CvN and CvI; Magel2 (melanoma antigen family L2), unique to CvI; and Ampd1 (adenosine monophosphate deaminase), also unique to CvI." (PMID 27782041, 2016).
congestive heart failure (2 papers, 2017 to 2024). Failure of the heart to pump a sufficient amount of blood to meet the needs of the body tissues, resulting in tissue congestion and edema. "Adenosine monophosphate deaminase 1 (AMPD1) c.34C>T (rs17602729) is involved in congestive heart failure, muscle metabolism, injury risk, and early fatigue during sports practice." (PMID 39125881, 2024).
rheumatoid arthritis (2 papers, 2013 to 2025). A chronic, systemic autoimmune disorder characterized by inflammation in the synovial membranes and articular surfaces. "Patients with rheumatoid arthritis treated with methotrexate carrying the C34T allele of the AMPD1 gene were shown to have better clinical response to the drug." (PMID 23733889, 2013).
cardiomyopathies (1 paper, 2025). "The review identified key gene variants affecting athletic performance: endurance (AMPD1, PPARGC1A), power (ACTN3, NOS3), strength (PPARG), and injury susceptibility (COL5A1, MMP3), while also examining inherited conditions like cardiomyopathies (MYH7, MYBPC3)." (PMID 40724525, 2025).
dilated cardiomyopathy (1 paper, 2020). Cardiomyopathy which is characterized by dilation and contractile dysfunction of the left and right ventricles. "There were some unusual clinical features and heterogeneity as well, such as that in AMPD1 associated myopathy where ranges from mild symptoms to severe limb-girdle features progressing fast to wheel-chair assistance and dilated cardiomyopathy were observed." (PMID 33250842, 2020).
endotoxemia (1 paper, 2011). "• The presence of the AMPD1 polymorphism is associated with increased levels of adenosine but does not affect the inflammatory response during human experimental endotoxemia." (PMID 21211004, 2011). "We studied the effect, in a separate group of healthy volunteers, of the common 34C > T variant of the AMPD1 gene on the adenosine concentration and subclinical end-organ damage during endotoxemia." (PMID 21211004, 2011).
lung carcinoma (1 paper, 2022). "Accordingly, lung cancer patients who express high levels of AMPD1 have a worse response to immunotherapy." (PMID 36439484, 2022). "Moreover, immunohistochemistry showed that the protein level of AMPD1 was higher in lung cancer." (PMID 36439484, 2022). "Moreover, AMPD1 was identified as a novel target for lung cancer immunotherapy." (PMID 36439484, 2022).
Myalgia (1 paper, 2013). "One of the downstream metabolites of this pathway, D-ribose, has been reported to alleviate symptoms of myalgia in patients with a congenital loss of AMPD1." (PMID 23785461, 2013).
myositis (1 paper, 2013). "Since patients with myositis are expected to have acquired deficiency in AMPD1 enzyme activity, treatment with D-ribose remained an untested potential therapeutic option." (PMID 23785461, 2013). "First, it has been observed that both patients and mice with myositis acquire a deficiency of the muscle specific enzyme AMPD1." (PMID 23785461, 2013). "We have now demonstrated that there is a deficiency of AMPD1 as well as hypoxanthine and other AMP breakdown products in myositis mice, but treatment of these mice with daily oral doses of D-ribose showed no beneficial effects." (PMID 23785461, 2013). "We have previously shown that decreased expression of a purine nucleotide cycle enzyme, adenosine monophosphate deaminase (AMPD1), leads to muscle weakness in a mouse model of myositis and may provide a mechanistic basis for muscle weakness." (PMID 23785461, 2013). "IMP is the immediate downstream product of AMPD1, and we found that IMP levels in the myositis mice were 24.6% lower than those in healthy controls." (PMID 23785461, 2013). "The genes for both AMPD1 and muscle creatine kinase (CKM) are known to be downregulated in humans and mice with myositis." (PMID 23785461, 2013).
sarcopenia (1 paper, 2023). Progressive decline in muscle mass due to aging which results in decreased functional capacity of muscles. "Our data provide molecular and metabolic evidence supporting the use of strategies aimed to improve insulin sensitivity and to block AMPD1 to prevent sarcopenia in subjects with CKD." (PMID 36994079, 2023). "Here, we provide evidence that the kidney-muscle crosstalk in sarcopenia is mediated by reduced insulin sensitivity and the activation of the muscle-specific isoform of AMP deaminase, AMPD1." (PMID 36994079, 2023).
thyroid cancer (1 paper, 2022). "In thyroid cancer, AMPD1 expression closely correlates with malignant evolution and the clinical prognosis of patients, and it is promising to become an important biomarker for immunotherapy." (PMID 36439484, 2022).
myopathy (6 papers, 2015 to 2025). A disease of the muscle in which the muscle fibers do not function properly. "These AMPD1 cases suggest more heterogeneity in the nature of muscle weakness and clinical overlap of AMPD1-associated myopathy with limb-girdle features in the Indian population." (PMID 33250842, 2020). "In the player group, the CT genotype of the AMPD1 gene was associated with significantly lower vertical jump height compared to the CC genotype (p < 0.05), consistent with previous studies linking the T allele to reduced exercise capacity, muscle fatigue, and myopathy." (PMID 40149402, 2025). "Since only a few part of AMPD1 C34T carriers exhibit muscular complaints, the clinical relevance of this myopathy has been questioned." (PMID 29095874, 2017). "The lack of AMPD1 enzyme has been associated with an increased frequency of mild forms of myopathy post-exercise, with lower time to fatigue and muscle cramping, though not all individuals with AMPD1 deficiency will experience these symptoms." (PMID 26716680, 2015). "Transcriptome analysis of skeletal muscle biopsies from ADSS1 myopathy patients revealed significant downregulation of all three purine nucleotide cycle (PNC) genes: ADSS1, adenylosuccinate lyase (ADSL) and adenosine monophosphate deaminase 1 (AMPD1)." (PMID 39593137, 2024). "Cardiac involvement was observed in a total of 6 patients: one each for AMPD1, GAA, DYSF, LMNA, and two GNE-myopathies." (PMID 33250842, 2020).